ENSG00000289723 (novel T cell receptor alpha variable)
Gene: T-cell receptor variable (V) gene on chromosome 14 (21,861,353 to 21,862,012, forward strand). Ensembl gene ENSG00000289723.
Gene Ontology:
Cellular component: plasma membrane